MBD3 (methyl-CpG binding domain protein 3)
Diseases named in the same sentence as MBD3 in open-access papers (continued):
Sharing a sentence is not in itself a finding about the gene and the disease.
cancer (continued). "Although Mbd3 activity is likely relevant to pathologies seen in cancer, neurological disease, and developmental defects, mechanisms underlying its regulation remain unclear." (PMID 28467410, 2017). "Therefore, more studies are needed to understand the function of MBD3 in somatic and cancer cell reprogramming." (PMID 27894081, 2017). "This decrease is likely due to the reduction in Dnmt1 binding throughout the genome we observed in Mbd3 KO cells, consistent with findings in cancer cell lines, although other mechanisms may also contribute to this phenomenon." (PMID 27849519, 2016). "Despite the absence of mutations in MBD2 or MBD3 in cancer, there is evidence that these genes show altered regulation in tumors." (PMID 27303433, 2016). "Therefore, the focus of studies on MBD2 and MBD3 in cancer has shifted to their potential as therapeutic targets." (PMID 27303433, 2016). "Interestingly, MBD3 protein was shown to be associated with the proximal promoter of CDKN1A and was released on treatment of cancer cells with a HDAC inhibitor." (PMID 23658227, 2013). "Interestingly, suppression of MBD3 expression modulated H3K27ac at regions connected with FGF, VEGF, JAK/STAT, MAPK and PI3K/Akt signaling, which are associated with resistance and more aggressive disease in various cancers." (PMID 34359703, 2021). "Similarly, the methyl-CpG-binding domain protein 3 (MBD3) subunit can interact with transcription factor JUN, an oncogene that plays critical roles in several cancers." (PMID 37046781, 2023). "Methyl-CpG binding domain protein 3 (MBD3) is a key epigenetic regulator involved in the progression and metastasis of several cancers, but its role in HCC remains unknown." (PMID 35501390, 2022). "While the target genes for MBD3 have not been identified in germ cells, depletion of MBD3 was found to induce arrest at the G2/M transition and result in defective mitosis in cancer cells." (PMID 34684636, 2021). "We examined whether the epigenetic silencing of CDKN1A by MBD3 and FBI-1 that we observed in various cancer and immortalized cells could also be possible in primary human cells such as HDFn cells." (PMID 23658227, 2013).
tumor (13 papers, 2004 to 2025). "To investigate the effect of MBD3 on mutant-allele tumor heterogeneity (MATH), we calculated their Pearson correlation in each tumor." (PMID 37370795, 2023). "In the light of the location of MBD3 in a region of chromosomal loss and its known functions in transcription suppression, it is considered as a candidate tumour-suppressor gene." (PMID 15138480, 2004). "The gene mutation landscape, tumor microsatellite instability, and t-SNE map of single-cell sequencing were also utilized to provide further insight into the role of MBD3 in tumor biology." (PMID 37370795, 2023). "An examination of the in vivo effect of the MBD3 revealed slow tumor growth in mice injected with sh-MBD3-transfected SW620 cells compared to control cells." (PMID 37370795, 2023). "The same results showed in Huh7 cells, when MBD3 was knocked down, both the volume and weight of subcutaneous tumours were significantly reduced and were partially recovered when MBD3 was re-expressed." (PMID 35501390, 2022). "MBD3 is significantly highly expressed in HCC, associated with the advanced tumour stage and poor prognosis in HCC patients." (PMID 35501390, 2022). "To identify the downstream target genes participating in tumour regulation in MBD3-mediated HCC, we compared the whole gene transcriptional profiles of Huh7-shNT cells and -shMBD3 cells by RNA-seq." (PMID 35501390, 2022). "Subcutaneous tumorigenesis experiments in BALB/c nude mice revealed that MBD3 knockdown in Huh7 cells significantly reduced tumour growth, which was partially rescued by TFPI2 co-suppression." (PMID 35501390, 2022). "The results showed that MBD3 overexpression in Hep3B cells led to a significant increase in tumour weight and volume." (PMID 35501390, 2022). "The PFS of GBM patients who received gross total resection in surgery and adjuvant therapies (i.e., radiotherapy and temozolomide) was highly proportional to the intra-tumor levels of MBD3 and 5hmC." (PMID 27835581, 2016). "We further uncover that depleting MBD3 enhances the transcription of the oncogenic miR-17-92 cluster at chromosome 13, therefore promoting tumor proliferation." (PMID 27835581, 2016). "In this regard, a group of patients bearing correlated levels of MBD3 and 5hmC in tumor biopsies were recruited." (PMID 27835581, 2016). "MTA2 and MBD3 might co-regulate tumor development through co-expression and physical interaction in the cell membrane, mitochondria, and nucleus, leading to tumor cell expression and migration." (PMID 37371463, 2023). "MBD3 plays a tumour-promoting role in HCC through epigenetic regulation of TFPI2 transcription." (PMID 35501390, 2022). "MBD3 can also participate in the occurrence and development of tumours." (PMID 35501390, 2022). "Moreover, soft agar colony-forming results revealed that the ability of Hep3B cells to form colonies in soft agar was largely enhanced with MBD3 expression and significantly impaired after MBD3 depletion, suggesting that MBD3 plays a role in tumour transformation." (PMID 35501390, 2022). "Based on our findings that MBD3 might play an oncogenic role in the development of HCC, we postulated that it may also be associated with alterations in migration and invasion: two biological actions essential for tumour metastasis." (PMID 35501390, 2022). "Many TFPI2 downstream signaling pathways are affected upon MBD3 depletion, such as matrix metalloproteinases (MMPs), PI3K and AKT, which are primary factors in tumour growth and metastasis." (PMID 35501390, 2022). "We identified that MBD3 plays a key role in promoting the proliferation, angiogenesis and invasion of HCC by inhibiting tumour suppressor TFPI2." (PMID 35501390, 2022). "Based on these important findings, we conclude that MBD3 can inhibit the expression of TFPI2, indirectly relieve the inhibitory effect of TFPI2 on tumour angiogenesis, and then promote tumour metastasis." (PMID 35501390, 2022).
tumor (continued). "Taken together, these suggest that MBD3 inhibits the expression of the tumour suppressor TFPI2, thereby undoing its inhibition of tumour angiogenesis, eventually promoting the progression and metastasis of HCC." (PMID 35501390, 2022). "MBD3 expression was significantly correlated with preoperative AFP level (P < 0.001), vascular invasion (P = 0.013), tumour capsule (P = 0.013), Edmondson grade (P = 0.005) and TNM-stage (P = 0.001)." (PMID 35501390, 2022). "MBD3 (top four) plays a significantrole in EMT process and tumour metastasis." (PMID 36124841, 2022). "We observed stronger MBD3-positive staining in HCC patients with a higher AFP level, no tumour capsules and poor cell differentiation." (PMID 35501390, 2022).
infection (5 papers, 2015 to 2024). The state of being infected such as from the introduction of a foreign agent such as serum, vaccine, antigenic substance or organism. "Infection with the wild-type bacterial strain resulted in lower mBD-3 mRNA levels in the trachea than in mice infected with the type III-deficient strain." (PMID 30154362, 2018). "The wild-type strain 297 (CSF) exhibited a peak of mBD-3 at 24h post-infection while the 1808/03 strain (CSF) induced a negligible amount of all three AMPs tested." (PMID 26197047, 2015). "In contrast, mBD-3, which is the equivalent of human BD-2, was secreted in the same high level in mice regardless of infection, while HT-29 cells, which do not express it under normal conditions, show high expression following infection." (PMID 34831214, 2021). "We performed real time qRTPCR for mBD2, mBD3 and Cnlp (CRAMP) before and 48 hours after infection." (PMID 26332373, 2015). "The study of AMP induction in mouse skin after infection with different B. burgdorferi strains showed an induction of CRAMP in the presence of the PBre strain, while MR726 and 297 strains induced the defensin mBD-3 (an ortholog of human defensin hBD-2)." (PMID 26197047, 2015).
MBD3 also shares sentences with these, for which no sentence is quoted: Epithelial Ovarian Cancer (2 papers); neurological disease (2); adenocarcinoma (1); Alzheimer disease (1); brain cancer (1); brain tumors (1); central precocious puberty (1); Diabetes (1); gastric cancer (1); intestinal tumor (1); liver cirrhosis (1); lymph node metastasis (1); neurodegenerative disease (1); ovarian cancer (1); Salmonella Infections (1); salmonellosis (1); schizophrenia (1).